IFNG (interferon gamma)
Diseases named in the same sentence as IFNG in open-access papers (continued):
Sharing a sentence is not in itself a finding about the gene and the disease.
tumor (continued). "Application of in vitro models, which mimic conditions of solid tumors, identified tumor lactic acidosis as one potent factor abrogating TCR-stimulated IFNg production by inhibition of p38 and JNK/c-Jun activation." (PMID 30400822, 2018). "The augmented CD200 expression not only attenuates antigen-specific Th1 cytokines such as IFNγ and TNFα production but also direct them to acquire Th2 phenotype (expression of IL-4/IL-10 cytokines in viral and tumor pathogenesis)." (PMID 29915577, 2018). "In this review, we conducted an extensive literature search of recent 5‐year studies about the roles of IFNγ signaling in both tumor immune surveillance and immune evasion." (PMID 30039553, 2018). "Fully polarized M1 macrophages produce proinflammatory cytokines including IFNγ, interleukin 12 (IL-12), and TNFα, that contribute to tumor rejection and antigen presentation." (PMID 29463044, 2018). "Analysis of the local response highlighted that particularly R-115 unleashed the immunosuppressive tumor microenvironment, i.e. induced immunomodulatory cytokines, including IFNγ, T-bet which promoted Th1 polarization." (PMID 30080893, 2018). "The expression of PD-L1 on tumor cells has been found to be regulated by several cytokines, including interferon gamma produced by T cells from tumor microenvironment." (PMID 29850620, 2018). "We performed IFNγ ELISPOT with isolated tumor infiltrating lymphocytes (TIL) from established subcutaneously implanted tumors." (PMID 29423108, 2018). "The other is a reactive, interferon-gamma (IFNγ) induced expression at the tumor-stroma margin, explaining its favorable role." (PMID 29942303, 2018). "Consistent with earlier findings, R848-treated mMDSCs lysed tumor targets as did cells cultured with IFNγ or the combination of IL-6 plus TNFα." (PMID 29632539, 2018). "Further analysis revealed that the increased CD8 TILs in CP1-administered tumors expressed increased TNFα and the activation marker PD-1, and a higher percentage expressed IFNγ within the tumor draining lymph nodes (dLNs)." (PMID 29686284, 2018). "A similar IFNγ expression phenotype was seen in tumor infiltrating CD8+ AH1-tet+ T cells from mice treated with ALX148 and in combination with anti-PD-1." (PMID 30133535, 2018). "Previous work has demonstrated that interferon-gamma (IFNɣ) secreted in the tumor microenvironment increases IDO1 expression, similar to PD-L1." (PMID 29805749, 2018). "We recently demonstrate that HSC differentiation into antigen presenting cells is driven by IFNγ from activated T cell within the tumor microenvironment." (PMID 30333482, 2018). "The clinical use of IFNγ immunotherapy should be considered to efficiently target the recruitment of proangiogenic monocytes and subsequent tumour growth." (PMID 29367702, 2018). "To determine whether signals associated with the tumor microenvironment can alter CD11b expression and subsequently affect myeloid cell polarization, we evaluated the effect of macrophage media (mCSF-, IL-4- and IFNγ/LPS) on cell surface CD11b expression in bone marrow derived macrophages." (PMID 30568188, 2018). "We have shown previously that the anti-tumor effect of Poly I:C requires CD8+ T cells, and that IFNγ production by CD8+ T cells is essential for anti-tumor activity." (PMID 30383838, 2018). "As a pleiotropic and critical cytokine in host immune activities and tumor rejection, IFNγ exerts its effects through a complex and orderly signaling pathway." (PMID 30294272, 2018). "TGFβi significantly increased IFNγ secretion against all tumor targets tested, and significantly increased TNFα secretion against all tumor targets except CHLA-255." (PMID 30400618, 2018). "Exposure of tumor cells to IFNγ is known to induce pro-inflammatory gene signatures that consequently lead to enhanced recognition by cytotoxic T-lymphocytes mediated by the up-regulation of the APPM and HLA surface expression." (PMID 29242379, 2018).
tumor (continued). "It is possible that tumor cells downregulate expression of IFNG as a mechanism for escaping from immune surveillance." (PMID 30336781, 2018). "In a transplantable model of peritoneal and ovarian cancer, γδ T17 (Vγ6+) cells were shown to preferentially produce IL-17 instead of IFNγ and to promote tumor growth." (PMID 30298063, 2018). "Activation of T lymphocytes by tumor antigen ultimately leads to production and secretion of IFNγ, a cytokine that stimulates TIL proliferation and differentiation, thereby enhancing TIL’s effector functions." (PMID 30409126, 2018). "IFNγ also has to act on the tumor stroma for effective elimination of large, established tumors, although it can inhibit tumor growth by acting directly on cancer cells." (PMID 30039553, 2018). "These neutrophils were able to secrete TNFα, which in combination with IFNγ, exerted synergistic cytotoxic effects on endothelial and tumor cells within the tumor microenvironment." (PMID 29765907, 2018). "This can occur in response to immune pressure, especially in the presence of IFNγ, in a process known as “acquired resistance”, and thus, inhibiting the function of T-cells within the tumour environment." (PMID 29570634, 2018). "CD4+ T cells recovered from GL261-immune C57BL/6 mice were used to detect tumor antigenic determinants presented by the BMDCs with the readout being the number of cells producing IFNγ." (PMID 30400835, 2018). "MDSC activation is initiated in response to IFNγ produced by anti-tumoral T cells in the tumor microenvironment." (PMID 30619850, 2018). "A better understanding of the roles of IFNγ in tumor escape and tumor elimination will better design clinical immunotherapy approaches and provide new insights into cancer biology." (PMID 30039553, 2018). "We show that blocking EGFR with cetuximab inhibits the activation of several pathways downstream of EGFR and results in an increased production of inflammatory chemokines and attraction of T cells when the tumor cells are stimulated with IFNγ and TNFα." (PMID 30192802, 2018). "In support of these survival observations, marked IFNγ secretion was detected from splenocytes harvested from vaccinated mice as late as 6 months following vaccination when cultured with WT tumor cells." (PMID 29377881, 2018). "Nude mice and IFNγ blockade were used to investigate the mechanism of LNT affecting on tumor angiogenesis." (PMID 30373628, 2018). "IFNγ can kill tumor cells directly or by recruiting and activating key immune subsets such as macrophages and NK cells that recognize tumor cells." (PMID 30458889, 2018). "IFNγ gene expression in tumor cells after talimogene laherparepvec treatment, increased CD8+ T cells and elevated PD-L1 protein expression were detected in cancers of the patients who responded to the combination therapy." (PMID 30409126, 2018). "To investigate the nature of B220+CD11c+NK1.1+ cells against metastatic tumour cells, we examined the IFNγ secretion capacity and NK cell cytotoxic activity." (PMID 29930175, 2018). "The combination leads to an increase in IFNγ expressing CD8+ T cells upon stimulation while the number of tumor-specific CD8+ T cells remained similar, as in a previously reported study of checkpoint inhibitor combinations." (PMID 30133535, 2018). "HOE642 + anti-PD-1 combination therapy reduced the CD4+ Treg cell counts while increased tumor infiltration of CD4+IFNγ+ T cells and CD8+ IFNγ+ T cells in GL26 tumors." (PMID 30333031, 2018). "Factors that influence PD-L1 expression include tumor hypoxia, a proinflammatory (interferon gamma) microenvironment that promotes cell death and survival, and tumor heterogeneity." (PMID 29470536, 2018). "Tumour-infiltrated lymphocytes kill tumour cells by cell-mediated cytotoxicity and IFNγ production in tumour immunity." (PMID 29367702, 2018). "Recently, several papers reported that immune checkpoint blockade therapy led to upregulation of IFNγ and in turn clearance of tumor cells." (PMID 30039553, 2018).
tumor (continued). "To test the activity of the ovarian TILs against tumour antigens, we co-cultured the TILs with autologous tumour cells and measured IFNγ release." (PMID 30039427, 2018). "Taken together, IFNγ can decrease tumor growth by acting not only directly on cancer cells, but also indirectly on endothelial cells and immune cells in the tumor microenvironments." (PMID 30039553, 2018). "NK cells expressing CD64/16A facilitated cell conjugation with antibody-bound tumor cells, cytotoxicity, and IFNγ production, demonstrating function by both components of the recombinant FcγR." (PMID 30574146, 2018). "Tumor tissue was processed to obtain single-cell suspensions for flow cytometry analyses Levels of TGFβ-1 in mouse tumor tissue homogenates and IFNγ in mouse plasma samples were measured by commercial ELISAs." (PMID 30400822, 2018). "Our finding is in accordance with previous studies showing that PD-L1 expression of MC38-transplanted tumors increases as a result of exposure to inflammatory cytokines such as interferon gamma (IFNγ), which is sufficient for tumor escape and immune evasion." (PMID 29296022, 2018). "Here, we examined (i) anti-tumor effects by measuring suppression of tumor growth, (ii) the degree of T-cell expansion and infiltration into the tumor, (iii) T-cells’ antigen experience and IFNγ production, (iv) TCR diversity." (PMID 29348598, 2018). "Splenic CD8 T cells were isolated from MC38 tumour‐bearing mice and co‐cultured with naïve or irradiated tumour cells in an ELISpot assay using interferon gamma as the readout." (PMID 30442705, 2018). "The expression of PD-L1 on tumor cells can be enhanced by IFNγ secreted by activated cytotoxic T cells in the tumor microenvironment, thereby downregulating antitumor immunity." (PMID 30147691, 2018). "Briefly, dCAR-T cells in mice bearing the cognate tumor cells (AsPC-1) released high levels of cytokines, including 2320 pg/mL IL-2, 609 pg/mL TNFα, 2486 ng/mL IL-6, and 67 ng/mL IFNγ, which was similar to that observed for cytotoxicity." (PMID 30103775, 2018). "The PDL1 expression on tumor cells can be upregulated by intrinsic oncogenic signaling pathways or by surrounding T cells through the IFNγ/STAT1/IRF1 pathway and chronic type I IFN exposure." (PMID 30305853, 2018). "The secretion of IFNγ and TNFα by NK cells in response to tumor target stimulation (DAOY) following overnight treatment with IL-2 was measured in supernatants at Day 7, 14, and 1 week, 3 weeks, and 1 month (33 days) post-expansion." (PMID 30400618, 2018). "This would occur as tumors surpass T-cells for glucose, directly sub-optimizing T-cell function by impeding their IFNγ production, critical for anti-tumor activity." (PMID 30191140, 2018). "TC1 primary tumour cells had higher levels of several immunostimulatory factors (IFNγ, IL-2, TNFα), including antigen presenting molecules (H2-K1) as compared to the A9 metastatic tumour cells." (PMID 29440650, 2018). "Bellucci et al45 showed that increased expression of PD‐L1 by tumor cells resulted in enhanced resistance to NK cell lysis, while blockade of IFNγ/JAK signaling pathway leads to higher tumor cell lysis mediated by NK cells." (PMID 30039553, 2018). "Surprisingly, the endothelial monolayer activation with IFNγ which was at high levels in SKBR7 tumours, showed a twofold increased adhesion of HPMo, but even less transmigration of these cells." (PMID 29367702, 2018). "More advanced post-cystectomy tumour stages correlated significantly with increased methylation at the IFNG -4229 bp locus." (PMID 30075815, 2018). "Decreased tumorigenesis occurred together with elevated production of chemokines in tumor cells and increased IFNγ-producing CD8+ and CD4+ (Th1) T lymphocytes in the tumor microenvironment." (PMID 30622432, 2018). "Administration of IFNγ, a stimulant of M1 polarization, achieved a favorable clinical outcome, with increased tumor cytotoxicity of TAMs in patients diagnosed with ovarian carcinoma." (PMID 30619850, 2018).
tumor (continued). "IFNγ functions as an important inducer of PD-L1 on the surface of tumor cells, and patients who have a better response to PD-L1 blockade also have increased IFNγ and IFNγ-inducible chemokines." (PMID 30294272, 2018). "In general, effector cells rejected the tumor cells, accompanying with cytokine release, including IL-2, TNFα, IL-6, and IFNγ." (PMID 30103775, 2018). "MACinflam produced in cultures containing IL-6 plus TNFα or IFNγ also mediated significant tumor cell lysis." (PMID 29632539, 2018). "This combination therapy resulted in the marked reduction of TNFR2 expression on tumor-infiltrating Tregs and consequently increases tumor infiltration of interferon-gamma-producing CD8+ CTL." (PMID 29967617, 2018). "LNT treatments elevated the expression of angiostatic factors such as IFNγ and also increased tumor infiltration of IFNγ-expressing T cells and myeloid cells." (PMID 30373628, 2018). "In all 4 cases, enhanced lymphocyte infiltration was observed when PBMC where incubated with tumor cell supernatant of cetuximab treated IFNγ/TNFα stimulated cancer cells." (PMID 30192802, 2018). "VE800 administration promoted enhanced accumulation of interferon- gamma producing CD8 T cells in the spleens of tumor-bearing mice indicating the consortium promotes systemic cellular immune cell activation." (PMID 30400822, 2018). "Although not meeting significance, this is likely to be the result of the improved efficacy of intra-tumoral Treg cell depletion observed for IgG1SDALIE relative to wild-type IgG1 and consequent higher production of IFNγ by CD4+eff T cells in the tumor." (PMID 29576375, 2018). "Tumour regrowth was associated with decreases in CD8+ T cells, NK cells, and loss of granzyme B and IFNγ production, confirming dampened inflammation." (PMID 30327563, 2018). "This led to the upregulation of IL-12 and IFNγ production and subsequent repolarization of the tumor-promoting M2 TAMs in the Ehrlich ascites carcinoma model." (PMID 30349530, 2018). "The expansion and activation of NK cells and antigen-specific IFNγ-producing CD8+ T cells are common targets for effective anti-tumor activity." (PMID 30383838, 2018). "Conditional activation of NOTCH1/2 in CD8 T-cells induces a robust and sustained anti-tumor response, resulting in increased IFNγ production and reduced tumor burden." (PMID 30967879, 2018). "Systemic treatment with Salmonella induced a Th1 inflammatory response at the tumor site, which was accompanied by macrophage and neutrophil infiltration and a significant increase in IFNγ production." (PMID 29765907, 2018). "Using a protease inhibitor to sensitize tumors to apoptosis resulted in enhanced IFNγ production, increased Fas expression and improved tumor lysis in vivo." (PMID 29464051, 2018). "More importantly, anti-PDL-1 antibodies can block tumor glucose utilization favoring T cell glycolysis and IFNγ release." (PMID 29515580, 2018). "PD-L1 expression in pre-treatment tumor or immune cells is upregulated as a consequence of proinflammatory cytokine interferon-gamma (IFN-γ) released from T cells activation, presumably by tumor-associated antigens within the microenvironment." (PMID 30631766, 2018). "The patients with LNs displaying low IFNG methylation, and therefore a Th1 signature, had a lower pathological tumour staging (pT stage), pTa-TisN1 (patient 6) and pT0 (patient 24), although the former had a node metastasis (not included in specimens)." (PMID 30075815, 2018). "Instead, the PD-L1 expression on tumor cells seems to be regulated by external factors and can be induced by cytokines (e.g., IFNγ) released by immune cells, growth factors or hypoxia." (PMID 29438316, 2018). "The cohort that received intratumor CCR2+HSCs had endogenous T cells isolated from tumor draining lymph nodes that mounted the capacity to recognize Ptc tumor cells, secreting IFNγ upon co-culture against Ptc tumor cell targets." (PMID 30333482, 2018).
tumor (continued). "MDSCs express high levels of IDO in response to IFNγ production and activation in the tumor microenvironment, creating yet another mechanism that drives their immunosuppressive phenotype during tumor progression." (PMID 30619850, 2018). "It has been shown by Parkhurst and colleagues that anti-CEA CAR-T cells proliferate in response to tumors overexpressing CEA, resulting in IL-2 and IFNγ cytokine secretion and tumor cell lysis." (PMID 30103457, 2018). "Collectively, our results indicate that effective immunotherapies in this model meet the following criteria: low DE50, high MFI of IFNγ venus signals in CD8+ T-cells and the presence of a large number of IFNγ+ CD8+ T-cells in the tumor." (PMID 29348598, 2018). "Interferon gamma was significantly increased in T cells from irradiated tumours with macrophage depletion having little effect." (PMID 30442705, 2018). "Consistent with previous data, LNT treatments alone reduced tumor vascular function, and IFNγ neutralization negated the effect of LNT treatments on tumor vascular function, indicating that IFNγ mediates the impact of LNT treatments on tumor vascular function." (PMID 30373628, 2018). "Although IFNγ is a potent anti-tumoral agent, it is reported to support tumor growth by increasing the proliferative capacity of the cancer cells and upregulating immune checkpoint inhibitors via a negative feedback loop." (PMID 29632539, 2018). "Such tumor antigen-targeting antibody-dependent cellular phagocytosis is observed to be more superior in TCMs and M1 (IFNγ + LPS) macrophages as compared to M2 macrophages (IL-4 + IL-13)." (PMID 30619850, 2018). "An increase in infiltrating cytotoxic CD8 T and NK cells to the tumor with complementary induction of dendritic cells, neutrophils and interferon-gamma-induced chemokines was observed in tumors after rucaparib+NKTR-214." (PMID 30400835, 2018). "IFNγ produced by T cells has, among its various biological functions, an essential role in the anti-viral and anti-tumor immune defense." (PMID 29970101, 2018). "Interferon gamma is produced by activated T cells, natural killer cells (NK) cells, the tumor microenvironment, and can lead to upregulation of both PD-L1 and PD-L2." (PMID 29368638, 2018). "MC38 TILs when co-cultured in the presence of MC38 tumor cells had significant levels of IFNγ production compared with irrelevant tumor cells." (PMID 30061886, 2018). "Milliplex® cytokine analysis revealed that IFNγ returned to baseline after 3 weeks, indicating a significant decline in tumour inflammation despite continued treatment." (PMID 30327563, 2018). "Taken together, these data suggest that LNT treatments suppress tumor angiogenesis via IFNγ and in a T cell-independent manner, which is correlated with an increase in IFNγ-expressing myeloid cells." (PMID 30373628, 2018). "NK cells isolated from human solid tumours have been found to be defective in their pro-inflammatory functions including IFNγ production and tumour cytotoxicity." (PMID 29904050, 2018). "(i) The pro-inflammatory cytokines IL-2, TNF, and IFNγ are important for a good T-cell response against the tumor." (PMID 29346301, 2018). "In vivo neutralization of IFNγ partially reversed the inhibition of tumor growth by LNT treatments compared with the control group, while IFNγ neutralization alone had little effect on tumor growth." (PMID 30373628, 2018). "In mouse models, fractionated doses (3 × 8 Gy or 5 × 6 Gy) were more effective than a single dose (20 Gy in 1 fraction) in enhancing the abscopal effect through the recruitment and activation of anti-tumor IFNγ-producing CD8+ T cells." (PMID 30487462, 2018). "When used with CAR T cells, it increased the infiltration of CAR T cells into the tumor site and enhanced the production and cytotoxicity of IFNγ, leading to complete cure of all treated mice." (PMID 29163850, 2017).